FOXP3 (forkhead box P3)
Diseases named in the same sentence as FOXP3 in open-access papers (continued):
Sharing a sentence is not in itself a finding about the gene and the disease.
infection (continued). "Compared to WT mice, lower numbers of CD4+CD25+FoxP3+ Treg cells were detected in lungs of IL-10−/− mice at the 16th week post-infection." (PMID 24205424, 2013). "Our lab has examined the role of CD4+ Tregs, and demonstrated that Forkhead box P3 (FoxP3)+ CD4+ T-cells increase during the first 2 weeks of infection and plateau at about 18 days post infection (dpi)." (PMID 23680027, 2013). "In this study, we confirmed that numbers of Foxp3+ T cells are elevated in the abomasa of animals in the early stages of infection when L4 stage parasites are predominant." (PMID 23964850, 2013). "In summary, this study demonstrates that ICOS plays key roles in eliciting Foxp3+ Treg-cell responses during infections with the nematode H. polygyrus and the trematode S. mansoni, both locally at the infection site and systemically within the LN and spleen." (PMID 23319295, 2013). "At 4 weeks post-infection, there were few Foxp3-expressing cells present in the granulomatous lesions of either WT or TLR2KO mice, although more were apparent in WT." (PMID 23785280, 2013). "In L. donovani-infected BALB/c mice, the number of splenic CD4+ CD127dimCD25+GITR+ T cells expressing higher Foxp3 and IL-10 increased at 21 days of infection." (PMID 22928057, 2012). "JES6-1 treatment on days 0, 2 and 4 of infection partially inhibits the expansion of the CD4+CD25+Foxp3+ cell population during acute malaria." (PMID 22272258, 2012). "This is true and a matter of debate, but our data showed a significant decrease in the number of CD4+CD25+ Foxp3+ Treg cells that was sustained up to week 10 of infection." (PMID 23226464, 2012). "The expression of FoxP3 as an indirect marker for the presence of naive regulatory T cells in the heart revealed a significant upregulation after infection." (PMID 22815907, 2012). "FOXP3 promoter site enrichment thus implicates regulatory T lymphocytes in the early phase of CA04 infection, possibly reflecting an increased requirement to confront the CA04-enhanced inflammatory response." (PMID 22937776, 2012). "The Foxp3 mRNA expression was increased after infection in the whole liver and mature granuloma samples." (PMID 22928057, 2012). "Adoptive transfer of in vitro generated CBA/Ca Foxp3+ T regulatory cells, via the tail vein, 2 hours prior to intranasal infection with S. pneumoniae led to a significant increase in mean survival of CBA/Ca mice (p<0.01)." (PMID 22563306, 2012). "Decreased fungal burdens and Foxp3+ Treg cells (CD4+CD25+Foxp3+), which were associated with increased numbers of effector CD4 T (CD44highCD62low) cells, were detected at week 2 post-infection." (PMID 23226464, 2012). "Several immune cell types, including tolerogenic DCs, myeloid suppressor cells, IL-10-producing CD4+ T cells, B cells and Foxp3+ T regulatory cells, have confirmed roles in the modulation and inhibition of inflammation in the context of infection." (PMID 22563306, 2012). "In L. infantum-infected BALB/c mice, CD4+CD25+ Foxp3+ cells expanded in a pooled fraction of draining lymph nodes and spleen cells at 7 and 28 days of infection." (PMID 22928057, 2012). "Herein, we investigate the host pathogen interaction that triggers these unfortunate outcomes, with particular focus on how prenatal infection impacts fetal tolerance sustained by expanded maternal Foxp3+ Tregs." (PMID 22916020, 2012). "In contrast, the capacity of moDCs to induce CD25 or FOXP3 was severely impaired by their in vitro infection with CCR5-utilizing virus." (PMID 22912740, 2012). "Brain and PBMC Foxp3 expression induced by P. berghei were significantly up-regulated in CXCL-10-/- mice at Day 4 post-infection compared with WT." (PMID 21439091, 2011). "In WT mouse brain, Foxp3 protein expression was significantly elevated at day 8 post-infection than at days 2 and 4, and in uninfected controls." (PMID 21439091, 2011).
infection (continued). "Infection with T. spiralis is accompanied by the accumulation of FoxP3+ Tregs in the infected muscles during the chronic phase of infection." (PMID 21793858, 2011). "Treg cells, identified by expression of the transcription factor Foxp3, are essential for preventing self-reactive immune responses and limiting immune-mediated tissue damage during infection." (PMID 21197439, 2011). "Forkhead transcription factor 3 (Foxp3) mRNA was significantly elevated at Day 4 post-infection (p < 0.05) when compared with control mice." (PMID 21439091, 2011). "Both proportions and absolute numbers of CD4+FoxP3+Tregs significantly increased within the mLN during acute infection, when anti-egg Th2 responses are at their peak." (PMID 21858239, 2011). "By contrast, RT-PCR analysis of the draining lymph nodes revealed little activity and only decreased FoxP3 mRNA levels followed upon infection." (PMID 21079691, 2010). "For example, molecules that have independently been associated with diminished Treg suppression potency such as reduced CTLA-4 and increased GITR expression were found for Foxp3+ Tregs from mice day 5 compared with day 37 after infection." (PMID 20714351, 2010). "A number of in vitro studies show preferential infection of Tregs with R5/X4 strains, which has been linked to this subset expressing high CCR5 and/or FoxP3 serving to directly active the HIV-1 LTR." (PMID 20174666, 2010). "Together, these studies comparing infection outcome after Treg ablation using Foxp3-specific reagents highlight interesting and divergent functional roles for Foxp3+ Tregs during specific infections." (PMID 20714351, 2010). "Using Foxp3GFP reporter mice for ex vivo isolation of regulatory T cells, we demonstrate that the dichotomy in infection tempo between early and late time points is directly paralleled by drastic changes in Foxp3+ Treg suppressive potency." (PMID 20714351, 2010). "Reciprocally, at later time points after infection when Treg suppressive potency is diminished, the relative contribution of Foxp3+ Tregs on T cell activation and bacterial clearance is reduced." (PMID 20714351, 2010). "At the same Treg to responder T cell ratio, Foxp3+ Tregs from mice day 5 after infection consistently inhibited responder CD45.1+ T cell proliferation (CFSE dilution) more efficiently." (PMID 20714351, 2010). "Intriguingly, the first infection study using Foxp3DTR mice for Treg ablation revealed somewhat paradoxical roles for Foxp3+ Tregs in host defense." (PMID 20714351, 2010). "The frequency and number of FoxP3+CD4+ Tregs was determined in each species as a function of time post-infection." (PMID 19214220, 2009). "Specifically, it was found that the Treg cells and their interaction with the FoxP3 transcription factor (CD4+FoxP3+ cells) allow for the preferential infection by HIV-1 in the Rag2-/-γc-/- animals." (PMID 19674458, 2009). "In contrast, PC61 (IgG anti-CD25) given in combination with 7D4 induced an approximately 50% reduction in the frequency of both CD25+ and Foxp3+ cells that was sustained throughout the 7 day infection period." (PMID 18401464, 2008). "During infection, like IL10 and TGF-β, the principal function of CD4+ CD25+ FoxP3+ Treg is the control of intense inflammation, induced at the site of infection, to avoid tissue damage." (PMID 18665224, 2008). "In these chimeras, infection with M. tuberculosis by aerosol route was better controlled when FoxP3+ T cells were depleted by anti-Thy-1.1 mAb treatment." (PMID 18665224, 2008). "It is important to note that since FoxP3 expression enhances VSV-G.HIV single-round infections, it likely affects an early, postentry step in viral replication." (PMID 15252446, 2004). "Likewise, a higher CD4+CD25+Foxp3+ T cell frequency was observed in animals from the Lb/HSP65 group only at 7 weeks post‐infection." (PMID 40745935, 2026).
infection (continued). "Further validation via Western blot analysis indicated that protein expression levels of IFN-γ, IL-4, IL-6, IL-17, TGF-β, GATA-3, T-bet, RORγt, and FoxP3 were significantly increased in the Pm_OMVs-infected group at 24 hours post-infection relative to the Pm group (P < 0.01)." (PMID 41306977, 2025). "Indeed, when individuals with up to 7 days of infection were included in the analysis, we observed an increase in the frequency of T cells with a regulatory and exhausted phenotype (PD‐1+ Foxp3+ CD25+ CD4+T cells)." (PMID 40388115, 2025). "Therefore, the result explained why the expression of Foxp3 increased in the late stage of infection in subsequent experiments." (PMID 39852910, 2025). "Additionally, EBV+ mice also showed substantially reduced hCD4+FOXP3+ Treg expansion, suggestive of an impairment in immune regulation due to prior infection." (PMID 40043135, 2025). "This discrepancy may stem from Foxp3-mediated suppression of Th17 differentiation and function by the highly expressed Treg cells during infection." (PMID 41035878, 2025). "Previous studies have shown that infection of T. gondii in mice during pregnancy reduces the quantity and suppressive capacity of Foxp3+ Treg cells, suggesting that adverse outcomes triggered by T. gondii are partially due to dysfunction of Foxp3+ Treg cells." (PMID 38632598, 2024). "Indeed, using adoptive transfers, Ballesteros-Tato and colleagues also noted that some CD4+FoxP3- cells upregulated FoxP3 after infection." (PMID 39319261, 2024). "However, examination of the proportion of Foxp3 expressing CD4 cells in LCMV infected animals showed that both genotypes exhibited a decrease in Tregs following infection." (PMID 38512979, 2024). "Due to the different effector immune response in the lungs of mice infected with either low or high dose of IAV, one might speculate that CD4+/CD25+FoxP3+ Tregs inhibit the T cell effector response after infection with a high dose of IAV." (PMID 38979428, 2024). "The level of FoxP3+was decreased significantly with increasing time points post infection." (PMID 36707891, 2023). "Therefore, we analyzed the ratio of spleen CD4+:CD4+Foxp3+ cells and found it to be significantly increased in the prime-boost vaccinated mice, which implies a better control of the infection than in the BCG-only vaccinated mice." (PMID 37108602, 2023). "Moreover, the increase of Foxp3+ cells was more severe in the vicinity of hyperplastic bile ducts during chronic states of infections." (PMID 38149297, 2023). "At 3 h post infection the FoxP3+ level was 63%, p = 0.0009 which decreased significantly at 6 h (36%, p < 0.0001), 12 h (27%, p < 0.0001) and finally decreased to the level 16% (p < 0.0001) at 24 h post infection when compared to the level expressed at 0 h post JEV infection." (PMID 36707891, 2023). "Furthermore, type 2 CD4+ST2+ T cell and CD4+Foxp3+ regulatory T cell numbers were also enhanced during infection." (PMID 36602520, 2023). "The deletion of Blimp-1 in T cells leads to a reduction of CD4+Foxp3+ T cells during the acute phase of infection and significantly decreased IL-10 production on day 12 post-infection, which could explain the observed increased inflammation." (PMID 37908369, 2023). "In our study, the increased Foxp3 and IL-10 expression suggests that Treg proliferation could be favored after infection." (PMID 36544518, 2022). "Furthermore, NK cell depletion significantly blunted the OVA-specific Tbet+ Foxp3– Th1 response following T1L infection." (PMID 35993365, 2022). "Since we observed lower IL‐10 levels in the spleen and lung of Sema3E-Fc treated mice and Treg is one of the primary sources of this cytokine, we next examined CD4+ CD25+ Foxp3+ T cells in the lungs of WT and Sema3E KO mice treated with Sema3E-Fc following Cm infection." (PMID 35983029, 2022).
infection (continued). "Regulatory T cells that express the transcription factor Foxp3 (Treg cells) are a highly heterogenous population of immunoregulatory cells critical for maintaining immune homeostasis and preventing immunopathology during infections." (PMID 36159872, 2022). "Besides, although the expression of Foxp3 was upregulated after infection with A. fumigatus in the lung of TLR2−/− mice and WT mice, those of TLR2−/− mice were also reduced compared to WT mice (p < 0.05)." (PMID 34222495, 2021). "Interestingly, we found that the frequency of PD-1hiIFN-γ+ cells among the viable FOXP3+ population consistently increased with HIV+ infection (staining controls)." (PMID 34446704, 2021). "Excitingly, infection with helminth parasites mediated by parasite-secreted proteins could also induce de novo T cell Foxp3 expression." (PMID 34691057, 2021). "However, we cannot exclude that the expansion of ST2+Foxp3+ Tregs has some benefits for the host during CR infection, as mice with Treg-specific ST2 depletion showed slightly increased colon pathology compared to animals with ST2-sufficient Tregs." (PMID 33654214, 2021). "Interestingly, women infected with Chlamydia trachomatis displayed increased expression levels of Foxp3 in vaginal swab samples following the clearance of infection due to antibiotic treatment." (PMID 34691057, 2021). "Alternatively, usage of transient depletion systems, such as the Foxp3DTR mouse model, would enable targeted elimination of all or some Foxp3+ Tregs prior to infection with SARS-CoV or SARS-CoV-2 in order to directly test the role of Tregs in SARS-CoV virologic and clinical outcomes." (PMID 33513210, 2021). "Moreover, the expression of TGF-β and Foxp3 correlates with IDO production during infection with Chlamydia trachomatis." (PMID 34093535, 2021). "Moreover, corneal herpetic lesions have an increased severity if the regulatory Foxp3(+)CD4+ Treg response is compromised from the onset of infection." (PMID 34054858, 2021). "Taken together, these data revealed that, although HIV infection led to the loss of CD4+ T cells, it resulted in an increase of a unique population of PD-1hiIFN-γ+AREG+FOXP3+ cells that survived the infection and might contribute to immune dysfunction." (PMID 34446704, 2021). "Indeed, the expansion of FoxP3+ Treg can be detected in the early phase of the Pf blood stage infection, subsequent to a TGFβ peak in the circulation." (PMID 34684226, 2021). "M.tb-specific FoxP3+ T cells have been currently discussed to enrich in mice peripheral lymphoid nodes after infection with M.tb; those Treg-like cells were activated by expressing high amounts of cell surface CD25, CTLA-4, GITR, CD103, and ICOS, but not producing IFN-γ." (PMID 33977110, 2021). "We also detected the expression of Foxp3 in the lungs of mice after infection with A. fumigatus." (PMID 34222495, 2021). "Our present results indicate an active induction of Treg by the parasite as follows: (i) Using an in vivo infection model for secondary AE, we observed a significant expansion of Foxp3 + Treg over effector T-cells in the peritoneum of mice in a time window around 7 days post infection." (PMID 32457746, 2020). "If confirmed in independent cohorts, enhanced FOXP3 expression by malignant T cells may have potential as a marker of infection-induced immune deregulation." (PMID 32409671, 2020). "Accordingly, differences in FOXP3 expression by malignant cells between SS patients and cohorts of patients may reflect differences in skin colonization and infection with SE-producing S. aureus." (PMID 32409671, 2020). "Foxp3+ Treg cells also expand during the infection, being more numerous in dLN." (PMID 32542003, 2020). "Interestingly, despite early increases in Foxp3+ T regulatory cell numbers in ST217-infected lungs, by 24 h post-infection D39-infected mice had significantly higher numbers of Foxp3+ cells." (PMID 32312961, 2020).
infection (continued). "First, cross-sectional assessments of FOXP3 and RORγt expressions at diagnosis may have been affected by subclinical infections with Th1 deviation." (PMID 32670274, 2020). "Furthermore, Foxp3+ cells from aged mice displayed lower levels of mTOR phosphorylation upon infection when compared to young mice (top and bottom)." (PMID 33240286, 2020). "Upon encounter of these antigens in infection, the strong TCR signal combined with the effects of pro-inflammatory cytokines at the infection site could destabilize Foxp3 expression, rendering Treg powerless or even converting them to effector T cells." (PMID 32131483, 2020). "Moreover, Treg-depletion prior to infection using anti-CD25 antibodies or genetic Foxp3-ablation enhances innate and adaptive immune responses and increases IFN-γ production of CD8+ T cells in ganglia." (PMID 32131483, 2020). "Interestingly, although the proportions of Foxp3+ regulatory T cells were increased, there was still a significant reduction in the overall number of Foxp3+ regulatory T cells in T cell–specific mTORΔ/Δ mice at the later stage of infection." (PMID 32817333, 2020). "On day 98 post infection, the relative amount of Foxp3+ Treg was slightly decreased whereas during the earlier progression of infection comparable frequencies of these cells could be detected in wild type and IL-6−/− mice." (PMID 33375150, 2020). "This process involves the CD8α+ DCs, which through TLR9-dependent recognition of the mtDNA (released from dead neutrophils) release IL-12p70, which generates FoxP3+Tregs from conventional CD4+T cells during a high dose infection, whereas a low dose infection induces CD8+T cell generation." (PMID 33643304, 2020). "Furthermore, CXCR3 receptor was highly expressed on the surface of CD4+ Foxp3+ cells during infection when compared to naïve cells." (PMID 32574175, 2020). "In addition, as observed in measles virus (MV)-infected rhesus macaques, Foxp3-expression in blood leukocytes correlated with slow viral clearance and prolonged infection." (PMID 32131483, 2020). "In addition, higher frequencies of regulatory CD4+FoxP3+ T cells are observed in C3H/HeN compared to C57BL/6 mice in the infection with R. conorii." (PMID 33091016, 2020). "Interestingly, we first found significantly higher levels of Foxp3+ cells in early infection compared to chronic infection in follicular areas, but not in extrafollicular areas." (PMID 30897187, 2019). "Moreover, up to 24% of the naïve CD4+T cells also differentiated to induced T regulatory (iTreg) phenotype (CD25+FoxP3+) in vaccinated mice before and challenge infection (*p < 0.01)." (PMID 31293599, 2019). "In addition, the number of Foxp3+ cells expressing CCR4+ was also increased at day 7 post infection." (PMID 31611578, 2019). "Given the stark baseline reduction in small intestinal Foxp3+ Tregs in Itgb8 (CD11c-Cre) mice, we utilised the DEREG mouse model, which allows specific ablation of Foxp3+ Tregs by injection of diphtheria toxin, to directly test the functional role of Foxp3+ Tregs during infection." (PMID 30998782, 2019). "T-bet+Foxp3+ Tregs have been observed in mice infected with Mycobacterium tuberculosis and Toxoplasma gondii suggesting these cells may be important in infections with intracellular pathogens that induce highly polarized Th1 responses." (PMID 30915078, 2019). "Using Foxp3-eGFP mice to accurately detect in vivo generated CD4+CD25+Foxp3+ Tregs, the infection with the S. aureus USA300 WT strain led to a significantly increased frequency (PBS: 11.2 ± 0.4%, WT: 17.6 ± 0.6%; mutant: 14.9 ± 0.6%) of Tregs in the spleen compared to PBS-treated mice." (PMID 31134074, 2019). "Interestingly, MAC-infected C3HeB/FeJ mice displayed increasing numbers of CD8+ T cells expressing IL-17 and Foxp3 over the course of the infection period but a modest increase of CD8+IFN-γ+ T cells." (PMID 31001241, 2019).